TERT (telomerase reverse transcriptase)
Diseases named in the same sentence as TERT in open-access papers (continued):
Sharing a sentence is not in itself a finding about the gene and the disease.
tumor (continued). "In human tumor cells, many endogenous proteins were confirmed interact with TERT and enhance telomerase activity." (PMID 36910209, 2023). "Through a gene expression microarray-based approach followed by GSE functional analysis the expression profile of 46 primary untreated ACC samples and of ACC (h-TERT) tumor cells was analyzed." (PMID 36720951, 2023). "Since these initial findings, TERT now has a well‐established role in tumour growth and development." (PMID 37041671, 2023). "Among them, three genes were repeatedly found to undergo HBV DNA integration in HCC tumor cells: TERT (n = 48), CCNE1 (n = 4), and KMT2B (n = 3)." (PMID 36672482, 2023). "Once classified as a tumor, patches correctly predicted as TERT positive were marked with a green color, but those predicted incorrectly were indicated with a purple color." (PMID 36984536, 2023). "The mechanisms by which the telomerase is de-repressed in tumor cells include amplification of the TERT gene, activation of oncogenes, such as MYC and specific mutations in the promoter of the TERT gene which promote the transcription of TERT." (PMID 37296851, 2023). "In conclusion, our results provide insight into the interdependency of various tumour-promoting factors and how short-term targeting of TERT can contribute to therapeutic effects beyond telomere maintenance." (PMID 37345011, 2023). "Variations of gender ratio, tumor grade ratio, IDH mutation rate, 1p19q codeletion rate, and TERT promoter mutation rate were <6.2% among the three datasets." (PMID 36688633, 2023). "Although specific impacts of each characteristic on immune infiltration have been reported, for instance, the telomerase catalytic subunit (TERT) activates endogenous retroviruses to promote the formation of a tumor immune suppression microenvironment." (PMID 37503331, 2023). "Within the training cohort, univariable analysis demonstrated that sex, HT, tumor size, tumor number, extrathyroidal extension, BRAF mutation, TERT promoter mutations and NRAS mutations were relative influencing factors of CLNM (P<0.05)." (PMID 36817603, 2023). "To examine the areas highlighted by the CRNN model in the tumor patches predicted to be TERT positive, we created attention maps for the CNN modules on the basis of the score values extracted from the last fully connected layers." (PMID 36984536, 2023). "TERT has been found to play multiple roles, including neuronal protection, anti-inflammation, antioxidant, tumor suppression, immunomodulation, and reduction of toxic proteins." (PMID 37063844, 2023). "Telomerase reverse transcriptase (TERT) can maintain the length of telomeres and promote the immortality of tumor cells." (PMID 36596785, 2023). "Specifically, the entropy feature was able to capture the heterogeneity of tumor microenvironment, which is a crucial factor in the development and progression of GBM and showed a strong correlation with TERT mutations." (PMID 38054695, 2023). "The miR-138 (i.e., miR-138-5p) is reported to be severely decreased in TC, contributing to the overexpression of TERT, tumor stage, and an invasive phenotype." (PMID 37569841, 2023). "Most prior studies correlated detection of mutations in particular genes such as TERT or BCL9 and RPS6KB1 with outcomes (OS and PFS) or advanced pathological features such as tumor size, PVTT, or TNM stage." (PMID 37762533, 2023). "Tumor cells are hallmarked by their capacity to undergo unlimited cell divisions, commonly accomplished either by mechanisms that activate TERT or through the alternative lengthening of telomeres pathway." (PMID 38136279, 2023).
tumor (continued). "iCluster1 tumours exhibited features such as higher tumour grade and presence of macrovascular invasion, a low frequency of CDKN2A silencing and CTNNB1 gene and TERT promoter mutations compared to iCuster2 and iCluster3." (PMID 36707636, 2023). "TERT amplification is pathophysiologically correlated with increased cancer cell immortality and tumor growth." (PMID 37848472, 2023). "Tumour size ≥20mm, especially in combination with other risk factors such as BRAF and/or TERT mutations or ETE, is an established risk factor for LN metastasis and recurrence." (PMID 37099203, 2023). "There are many studies on cancer gene therapy that used tumor-specific promoters such as promoters of TERT and PSA genes." (PMID 38017385, 2023). "In this aspect, The Cancer Genome Atlas (TCGA) as a useful resource that provides a large repository of tumor specimens, and several groups have analyzed TERT and telomerase by using this database." (PMID 36239411, 2023). "p-TERT pathogenic DNA sequence variants exclude the possibility of ATRX loss, as they both lead to the same consequence of telomerase activation within the tumor cell." (PMID 37908227, 2023). "They further showed in vivo that the downregulation of TERT via siRNA reduced the size of lung xenograft tumours due to apoptotic induction." (PMID 36579897, 2023). "While TERT inhibition is used to suppress tumor cells, TERT overexpression can also be used to treat cancers: it is considered a prominent way to improve immune cell functioning and expand their persistence." (PMID 37189709, 2023). "TERT promoter mutations serve as a pivotal oncogenic driver in GBM, facilitating telomerase activation and conferring unimpeded tumor growth and progression." (PMID 37830090, 2023). "Among the 24 TERT-rearranged tumor samples from 23 unique patients, material was available for the C-circle assay for all but one sample." (PMID 38136279, 2023). "On the other hand, Barthel and colleagues observed the expression of TERT was present in almost 75% of the analyzed tumor samples, with 31% of samples exhibiting alterations in the TERT promoter and 53% showing methylation patterns." (PMID 36810441, 2023). "It has shown that the TERT promoter is hypermethylated in both tumor tissues and cancer cells and is positively correlated with TERT mRNA expression and telomerase activity." (PMID 37575241, 2023). "We used RNA sequencing data from The Cancer Genome Atlas (TCGA) in 11 solid tumor types to investigate potential interactions between TERT expression, and B and T cell infiltrate in the tumor microenvironment." (PMID 36909826, 2023). "In recent years, several studies have employed RT-qPCR to detect circulating tumor cells (CTCs) expressing TERT and other molecules in peripheral blood." (PMID 37612721, 2023). "To investigate the role of TERT during tumor rejection, we correlated immune signatures with TERT expression." (PMID 37418389, 2023). "Of note, Lewis cell extracts exhibited a lower telomerase activity compared to that observed in LLC-challenged mice, indicating a possible interaction of tumor cells with the microenvironment, that induces the expression of TERT in the tumor cells." (PMID 37085672, 2023). "In view of the widespread abnormal hypermethylation of the TERT promoter in different tumor types, many scholars have also explored its clinical prognostic value." (PMID 37575241, 2023). "Recent studies have demonstrated that activation of PI3K/Akt mediates TERT upregulation to promote tumour cell proliferation." (PMID 36938425, 2023). "To investigate the role of TERT in TNBC, we analyzed TERT expression in both tumor tissues and normal tissues." (PMID 37575241, 2023). "Overall, this study uncovers the singularity of TERT compared to other conserved tumor antigens and the potential importance of a TERT-based B-T cooperation in the generation of an active antitumor immunity providing clinical benefit in HNSCC." (PMID 36909826, 2023).
tumor (continued). "TERT is the key rate-limiting catalytic subunit of telomerase and most tumor cells maintain telomere length by abnormally upregulating TERT expression." (PMID 37575241, 2023). "In fact, patients with histologically “low-grade” IDH-wildtype tumours that harbour EGFR amplification, +7/−10, or TERT promoter mutations demonstrate similar patient outcomes to those patients with IDH-wildtype tumours with high-grade histologic features." (PMID 37239289, 2023). "TERT promotertypermethylation plays an important role in TERT expression regulation and tumor microenvironment in TNBC." (PMID 37575241, 2023). "The telomerase reverse transcriptase (TERT) promoter, a tumor-specific promoter, was used to drive CCRS expression." (PMID 36650600, 2023). "Of interest, TERT is suggested to regulate key components of the tumor microenvironment such as inflammation and immunosuppression, and fibroblast activation in multiple cancers other than NSCLC." (PMID 37085672, 2023). "TERT Promoter Mutations: Mutations in the telomerase reverse transcriptase (TERT) promoter are often seen in aggressive PTC and are associated with increased tumor aggressiveness and poor prognosis." (PMID 37795362, 2023). "For the differentiation between tumor and non-tumor tissue the ROC analysis revealed an AUC of 0.73 (95% CI 0.66, 0.80) for TERT and 0.72 (95% CI 0.65, 0.79) for MYC." (PMID 37858127, 2023). "Hypermethylation of telomerase reverse transcriptase (TERT) gene promoters has been shown to enhance TERT expression in most tumor types." (PMID 36875059, 2023). "In fact, during this study, some GC with uncertain malignant features according to morphological analyses, were shown to express tumor markers such as TERT, AMACR, or PSMA." (PMID 37444476, 2023). "TERT is a key player supporting immortality of cancer cells and the amplification of TERT with other chromosomal aberrations plays a role in tumor development and progression." (PMID 37858127, 2023). "Since TERT is expressed in the vast majority of tumor cells this intratumor mechanism would result in immunity against cancer cell growth and local invasion." (PMID 36909826, 2023). "A biological link between tumor telomeres and glycolytic metabolism is established through the TERT or ALT pathway." (PMID 38090478, 2023). "Since no other conserved tumor antigen tested yielded a significant positive correlation, a plausible conclusion is that TERT is preferentially engaged in the activation of adaptive immune cells in the HNSCC tumor microenvironment." (PMID 36909826, 2023). "Intriguingly, systematic analysis of mutated tumor genes identified EGFR, MET, BRAF, and TERT as determinants in LUAD, and NOTCH, FGFR1, SOX2, and PI3CA as determinants in LUSC." (PMID 37046851, 2023). "Telomerase reverse transcriptase (TERT) is a conserved self-tumor antigen overexpressed in ∼85% of tumor cells and is immunogenic in cancer patients." (PMID 36909826, 2023). "This function appears to be one of the many ways tumours promote cell survival via TERT, aside from its canonical role of maintaining critically short telomeres." (PMID 37041671, 2023). "The tumor was WHO grade 2–3 and next-generation sequencing was notable for TERT promoter mutation, homozygous deletion of CDKN2A, and high variant allele frequency of NF2." (PMID 37025757, 2023). "The knockdown of ELF4 can inhibit TERT activation in HCC tumor cells, providing a new therapeutic target." (PMID 36672482, 2023). "In particular, several studies have shown that circulating TERT mRNA is an independent prognostic marker for various tumor types, including gastric, prostate, lung, and colorectal cancers." (PMID 36980987, 2023).
tumor (continued). "Even so, previous work, including our own, shows that TERT VAF is a reliable tumor purity marker in the majority of IDHwt GBM cases." (PMID 37919784, 2023). "Canonical TERT promoter mutations (g.1295113) had an independent hazard ratio (HR) that was equal to that of grade (TERT: HR = 2.2, p = 0.003, tumour grade: HR = 2.2, p = 2e−13), pointing to the benefit of TERT as a biomarker." (PMID 36042521, 2022). "The relationship of other clinicopathological features, including tumor grade, histological diagnosis, IDH mutation status, 1p/19q codeletion, TERT promoter status, ATRX status, and MGMT promoter status, with the TrMRS were also given out." (PMID 36386216, 2022). "Recent advancements in DNA isolation and NGS methods have facilitated the sensitive detection of TERT mutations in the formalin-fixed, paraffin-embedded (FFPE) tumor tissues." (PMID 35135543, 2022). "TERT overexpression induces tumor-like hyperproliferation, which is unfavorable for tissue and organ stability." (PMID 35582621, 2022). "Co‐FISH analysis of 5p‐end and TERT loci showed a more relaxed chromatin configuration in short telomere‐length tumours compared to normal telomere‐length tumours." (PMID 35979662, 2022). "TERT expression correlates with telomerase activity, which is required for tumor survival and unlimited proliferative capacity of cancer cells." (PMID 35668533, 2022). "siRNA loaded PILPs resulted in a significant down-regulation of EGFR and TERT expression paralleled by a reduction of tumor growth in a xenograft mouse model of HCC." (PMID 36297407, 2022). "We also found that overall outcomes were worse in patients whose tumours had TERT hypermethylation (n = 68, HR = 3.4, p = 0.01)." (PMID 36042521, 2022). "We sequenced the cfDNA and their peripheral blood mononuclear cell–derived normal counterparts using a custom UMI-tagged assay targeting the exonic regions of 75 genes commonly altered in HCC and TERT promoter, and the tumor biopsies using WES (n = 29)." (PMID 35263170, 2022). "Point mutations in the TERT promoter region can increase the transcription of TERT enzyme, extend the telomere length of cells, and enable tumor cells to gain unlimited replication." (PMID 35747806, 2022). "The spectrum of alterations that have been shown to increase TERT expression across tumor types are broad." (PMID 34549366, 2022). "Tumours with IDH1 or IDH2 mutations or those that are IDHwt have significantly different genetic pathways and outcomes in relation to TERT mutation." (PMID 36042521, 2022). "We found that besides the reported oncogenic role of GABPB1 in activating TERT, it also has tumor-suppressive functions in TC." (PMID 35326537, 2022). "Recent work has correlated prevalence of TERT promoter mutations with increasing malignancy in fibro-epithelial lesions, suggesting a mechanistic role for TERT alterations in the progression of these tumours." (PMID 34322734, 2022).
tumor (continued). "Of note, several oncoproteins encoded by human tumor viruses, such as HPV E6, EBV LMP1 and HHV-8 LANA, transactivate TERT gene leading to the immortalization and transformation of human epithelial cells." (PMID 36358677, 2022). "Patients with a TERT promoter wild type and EGFR wild type tumor had approximately double the overall survival of patients harboring a TERT promoter wild type tumor with EGFR alteration, with an overall survival of 26.6 vs. 13.3 months." (PMID 36233828, 2022). "TERT is the catalytic subunit of telomerase, which activates telomerase to maintain the integrity of telomerase and enables tumor cells to obtain infinite proliferation." (PMID 36741696, 2022). "The upregulation of the TERT gene in BC leads to the activation of telomerase, which contributes to the growth advantage and survival of tumor cells." (PMID 35563554, 2022). "Loss of tumor suppressors NF1 and PTEN were reported, and TERT, a gene encoding a telomere maintenance protein enabling replicative immortality, was amplified." (PMID 35229492, 2022). "In most differentiated cells, telomerase activity is absent due to the default repression of the TERT gene; however, TERT induction and telomerase activation occur widely in tumor development." (PMID 35326537, 2022). "PTEN is a tumor suppressor that inhibits phosphatidylinositol-4,5-biphosphate 3-kinase (PI3K)/AKT-serine/threonine kinase (AKT) signaling; consequently, TERT-induced PTEN silencing causes increased AKT activity and cell survival and proliferation." (PMID 36358677, 2022). "Integrated work-up of the first tumor manifestation showed an IDH1 R132H mutation with IDH2 wildtype and TERT C250T promoter mutation." (PMID 35018523, 2022). "Distance analysis between probes using high‐resolution confocal microscope (Leica SP8) furtherly confirmed that median distance between 5p‐end and TERT signals was superior in short telomere tumours (n = 3) than in normal telomere length tumours (n = 3)." (PMID 35979662, 2022). "Cantide, the h-TERT antisense nucleic acid drug, inhibits tumor cell growth and reduces h-TERT mRNA expression and telomerase activity." (PMID 36569303, 2022). "Rearrangement events occurring within the TERT promoter region have been documented in select tumor types and are thought to upregulate TERT expression by juxtaposing the TERT coding sequence to strong enhancer elements." (PMID 34549366, 2022). "The potential functions of telomerase and TERT in neural crest development and how these functions relate to the linkage between telomerase and NB tumor cell differentiation warrant further investigation." (PMID 36030273, 2022). "Transcriptional analysis of telomere maintenance genes reveals an upregulation of TERT and other four telomerase holoenzyme complex genes in poor prognosis tumours." (PMID 35979662, 2022). "Significantly, TERT is considered to be a marker of tumor cells because of the wide area of activation during tumorigenesis." (PMID 36119095, 2022). "Restricting our analyses to high-grade tumours and excluding tumours in the hands and feet, we found that patients whose tumour harboured both IDH1 and TERT mutations had significantly worse outcomes than those with an IDH1 mutation alone." (PMID 36042521, 2022). "In PTCs, all tumours carrying the mutant TERT promoter expressed TERT mRNA, whereas TERT mRNA was only detectable in approximately 1/3 of WT‐promoter‐bearing tumours." (PMID 36394204, 2022). "Analysis of the recurrence revealed an analogous molecular profile: The tumor showed an IDH1 R132H mutation with IDH2 wildtype and TERT C250T promoter mutation." (PMID 35018523, 2022). "In comparison, “hotspot” TERT promoter alterations are relatively rare in this tumor type along with TERT promoter rearrangements, and the latter are poorly characterized and under-recognized." (PMID 34549366, 2022).